BRAF (B-Raf proto-oncogene, serine/threonine kinase)
Diseases named in the same sentence as BRAF in open-access papers (continued):
Sharing a sentence is not in itself a finding about the gene and the disease.
melanoma (continued). "The development of strategies to manage and overcome acquired BRAF inhibitor resistance is now the major challenge facing the melanoma research community." (PMID 21505227, 2011). "Since fistulae are environments that experience permanent inflammatory processes, the fact that the fistula melanoma reported here is carrying the T1799A transversion supports the hypothesis that oxidative damage caused by free radicals plays a role in the genesis of BRAF mutations." (PMID 21827678, 2011). "In BRAF wild-type (BRAFWT) melanoma cells, the MAPK kinase pathway is activated by vemurafenib (and the analogous PLX4720) leading to upregulation of MEK and ERK and enhanced proliferation." (PMID 22175026, 2011). "There is now good evidence that mutated BRAF is a key initiating event in melanoma development and that continuous BRAF signaling is required for melanoma progression." (PMID 21505227, 2011). "Approximately 20% of BRAF V600E mutant melanoma patients on the phase I trial of vemurafenib appeared to be intrinsically resistant and did not meet the RECIST criteria for a response." (PMID 21505227, 2011). "The current study uses BRAFV600E expressing WM793 melanoma cells to derive data aimed at investigating the molecular determinant of cell invasion following treatment with clinical BRAF inhibitors." (PMID 21917148, 2011). "In another example, moderate micomolar RAF inhibitor PLX4720 is potent in inhibiting downstream signaling and proliferation of the cell harboring BRAF, and in treating melanoma cell lines." (PMID 21552547, 2011). "We then constructed a doxycycline-inducible myc-tagged RND3 expression system to determine if reduced RND3 expression was required for melanoma invasion in the presence of BRAF inhibitors." (PMID 21917148, 2011). "In contrast, modules associated with mutations of APC and BRAF possess tissue-specific patterns, as APC and BRAF mutations occur primarily on colon cancer and melanoma samples respectively." (PMID 22051105, 2011). "The sustained clinical activity of the BRAF inhibitor vemurafenib (PLX4032/RG7204) in patients with BRAFV600 mutant melanoma is limited primarily by the development of acquired resistance leading to tumor progression." (PMID 22194965, 2011). "The present work identifies factors that facilitate the residual invasion of BRAFV600E expressing melanoma cells after pharmaceutical BRAF inhibition by employing 2-D and more physiological 3-D preclinical models." (PMID 21917148, 2011). "Specifically, eight of 20 patients with BRAF mutant melanoma treated with GSK2110212 had a confirmed response with two patients achieving a CR." (PMID 22175026, 2011). "In melanoma, many studies have focussed on the copy number and gene expression levels of the BRAF, PTEN and MITF genes, but little has been done to identify new genes using these parameters at the genome-wide scale." (PMID 21494657, 2011). "Current single-agent HDACI trials show promising results in melanoma patients and combinations with selective BRAF inhibitors are planned." (PMID 21139585, 2011). "These cell lines are representative of different oncogenic events in melanoma and include 10 cell lines with a BRAF (BRAFV600E) and 7 cell lines with an NRAS (NRASQ61L or NRASQ61K) mutation." (PMID 21609436, 2011). "Mutations in BRAF, a regulator of the mitogen-activated protein-kinase kinase (MAPKK)-ERK1/2 pathway, are associated with approximately 70% of melanomas; the most common mutants are BRAFV599E and BRAFV600E." (PMID 21386910, 2011). "In addition, while BRAF mutations are seen in the great majority of melanocytic nevi, vertical growth phase melanomas, and metastatic melanoma, they are rarely detected in radial growth phase melanomas (10%), which is thought to be the initial malignant lesion prior to a frankly invasive lesion." (PMID 22175026, 2011).
melanoma (continued). "In the first trial, three of eight with advanced melanoma patients treated with AZD6244 achieved a partial response; BRAF and NRAS mutational status was unavailable." (PMID 22175026, 2011). "Documented sensitivity of melanoma cells to PLX4720, a selective BRAFV600E inhibitor, is based on the presence of mutant BRAFV600E alone, while wt-BRAF or mutated KRAS result in cell proliferation." (PMID 21738740, 2011). "This study demonstrates that a subpopulation of melanoma cells can survive and invade a dermal-like extracellular matrix, despite BRAF inhibitor treatments." (PMID 21917148, 2011). "These were characterized by karyology, growth kinetics, and genotyping for the BRAF and NRAS mutations common in melanomas and nevi." (PMID 21418545, 2011). "In one case, the BRAF-mutant melanoma cells that had been maintained in medium containing the B-Raf inhibitor AZ628 shifted their dependence from B-Raf to Raf-1." (PMID 21411864, 2011). "Primary resistance to BRAF inhibition is seen in less than 10% of patients with BRAF mutant melanoma treated with vemurafenib." (PMID 22175026, 2011). "Another possibility is that RAS/RAF/MEK/ERK signalling is still subject to regulation in melanoma cells even in the presence of constitutively active BRAF." (PMID 21224857, 2011). "Recently, advances have been made which are revolutionizing the standard of care for patients with BRAF mutant melanoma." (PMID 22175026, 2011). "In melanoma BRAF has been shown to activate NFAT to direct transcription of cyclooxygenase, a process which is also antagonized by tacrolimus." (PMID 21673995, 2011). "Interestingly, the amplification of CCND1 is relatively rare in melanomas with BRAF-NRAS mutations and may have similar effects on melanoma cell growth as the activation of the mitogen-activated protein kinase (MAPK) signaling pathway resulting from BRAF and/or NRAS mutations." (PMID 21911917, 2011). "The establishment of single-agent efficacy of selective BRAF inhibitors, and to lesser extent MEK inhibitors, is a major breakthrough for the treatment of patients with BRAF mutation positive melanoma." (PMID 22175026, 2011). "In melanoma, it has been shown that both growth factors and cytokines rescue cells from apoptosis after siRNA-induced knockdown of BRAF." (PMID 20531415, 2010). "MTA inhibits melanoma cell proliferation and in vivo tumor growth particularly in BRAF mutant melanoma cells." (PMID 20529342, 2010). "The triarylimidazole 1j with a phenylpiperazine ring D is the most promising compound, with nanomolar activity in the mutant BRAF inhibition assay, the cellular pERK inhibition and the mutant BRAF melanoma WM266.4 growth inhibition." (PMID 20667740, 2010). "Two human melanoma cell lines were used: CHL-1 with WT BRAF/WT NRAS and SKMEL28 with V600E mutant BRAF/WT NRAS." (PMID 21037799, 2010). "Dose response analyses showed that all the BRAF mutant melanoma cell strains were highly sensitive to PLX4032 with IC50 in the nM range (60–450 nM), whereas BRAF wild-type cells were resistant, with IC50 2.4 μM or above, consistent with published information." (PMID 20149136, 2010). "Several genes involved in the development of melanoma, including microphthalmia-associated transcription factor (MITF), c-Kit, V-raf murine sarcoma viral oncogene homolog B1 (BRAF) and neuroblastoma RAS viral oncogene homolog (N-RAS)." (PMID 24281076, 2010). "A recent phase I clinical trial of the BRAF inhibitor PLX4032 has validated this concept and showed that most patients whose melanomas harboured the BRAF V600E respond well to this treatment." (PMID 20531415, 2010). "We have examined the role of BRAF and NRAS mutations and reduced gene dosage at 9p in melanoma relapse." (PMID 20140953, 2010). "PLX4720 inhibits V600E BRAF melanoma cells, with an IC50 of 13 nM, accompanied by potent inhibition of phosphorylation of ERK, which leads to cell cycle arrest and apoptosis." (PMID 24281076, 2010).
melanoma (continued). "Recently, B-RAFV600E-dependent genes were analysed by MEK inhibition or BRAF siRNA in human melanoma cell lines, revealing regulation of the transcription factors FOSL1 and EGR1 by this pathway." (PMID 20663135, 2010). "BRAF and NRAS mutations have also been found in benign nevi and are therefore thought to be involved early in melanoma carcinogenesis." (PMID 20140953, 2010). "We report an investigation of gene dosage at 9p21.3 and mutations in BRAF and NRAS, as predictors of relapse and histological markers of poor melanoma prognosis." (PMID 20140953, 2010). "BRAF controls proliferation of human melanoma cells through the regulation of cyclin D1 and cyclin-dependent kinase inhibitor p27Kip1 protein." (PMID 20485284, 2010). "Melanoma cell lines harboring wild type NRAS and BRAF (37-31E and MeWo), NRASQ61L mutation (SKMel 103 and SKMel 147) or BRAFV600E mutation (UACC903, Colo 829) were grown in complete medium and in the presence of increasing concentrations of MTA." (PMID 20529342, 2010). "Recent work identified several genes required for the BRAFV600E-induced senescence and showed that in the context of BRAF mutation, expression loss of one of them, IGFBP7, is critical in promoting the progression to melanoma." (PMID 20975957, 2010). "More importantly, BRAF-selective drugs have recently entered the clinic and are producing excellent responses in patients with BRAF mutant melanoma." (PMID 20141835, 2010). "Given that ATF2 affects activity of the oncogenes N-Ras (mouse model) and BRAF (melanocyte growth on soft agar); we expect that ATF2 play significant roles in melanomas that carry either of these mutations." (PMID 21203491, 2010). "In these reports, the investigators also observed that selective BRAF inhibitors, such as PLX4720, 885-A and GDC-0879 stimulated MEK–ERK signaling in BRAF wild-type melanoma and carcinoma cells via RAF1 activation." (PMID 20149136, 2010). "Kinase-dead BRAF mimics the effects of the BRAF-selective drugs and kinase-dead Braf and oncogenic Ras cooperate to induce melanoma in mice." (PMID 20141835, 2010). "We used several human and mouse melanoma cell lines having different mutational status respect RAS, and BRAF proteins, and investigated the inhibition capabilities of MTA in vitro." (PMID 20529342, 2010). "The presence of ulceration is an important prognostic factor for melanoma even in stage III or metastatic disease and, therefore, we also assessed the associations between CDKN2A deletion and BRAF/NRAS mutation and ulceration." (PMID 20140953, 2010). "The aim of this study was to better understand the responses that melanoma cells make to BRAF-selective inhibitors and thereby to provide a molecular basis for the design of clinical trials using BRAF drugs." (PMID 20141835, 2010). "Examination of MEK, the upstream activator of ERK, showed a similar pattern of inactivation and activation in response to PLX4032 (pMEK), demonstrating that while the RAF-MEK-ERK pathway was inhibited in BRAF mutants, it was activated in BRAFwt melanoma cells." (PMID 20149136, 2010). "In vitro experiments showed that MTA treatment inhibited melanoma cell proliferation and viability in a dose dependent manner, where BRAF mutant melanoma cell lines appear to be more sensitive." (PMID 20529342, 2010). "Treatment of melanoma cells with increasing concentrations of the BRAF inhibitor PLX4720 led to a dose-dependent reduction in the growth of BRAF-V600E-mutated melanoma cell lines (WM35, WM164 and 1205Lu)." (PMID 20531415, 2010). "In the zebrafish melanoma models, testing the function of new and known genes that collaborate with BRAF to promote melanoma progression and invasion is an important next step." (PMID 20230482, 2010). "Some preliminary evidence suggests that inhibition of targets downstream of mutant BRAF in melanoma can inhibit lung metastasis." (PMID 24212610, 2010).
melanoma (continued). "The induction of apoptosis induced was slow in onset (>24 h), but very BRAF specific, with very little apoptosis observed in melanoma cell lines that were BRAF wild type." (PMID 20531415, 2010). "This metabolic signature correlated with inhibition of Hsp90 and downstream growth arrest and induction of differentiation in both melanoma cell lines used here, suggesting that it is likely to be BRAF statusindependent." (PMID 21037799, 2010). "To investigate the therapeutic potential of MTA we performed in vitro proliferation and viability assays using six different mouse and human melanoma cell lines wild type for RAS and BRAF or harboring different mutations in RAS pathway." (PMID 20529342, 2010). "Another important oncogene in melanoma is NRAS, and mutations in NRAS or BRAF are detected in almost all human melanoma." (PMID 20230482, 2010). "Erk1/2 kinase is downstream of BRAF and NRAS pathways, which are frequently mutated in human melanomas." (PMID 20701798, 2010). "Somatic mutation frequencies of BRAF and NRAS, two signature oncogenes in melanoma, exhibit differential preferences for primary tumors arising from different anatomic sites associated with varying UV exposure histories." (PMID 20520718, 2010). "Surprisingly, the inhibition of Erk1/2 pathway in BRAF mutant melanoma cell lines subjected to metabolic stress resulted in an increase in the number of dead cells." (PMID 19274086, 2009). "In melanoma cells harboring an NRASQ61L or NRASQ61K mutant allele, we find that targeting NRAS alone or both BRAF and CRAF in combination or both BRAF and PIK3CA together showed efficacy." (PMID 19492075, 2009). "Regarding genetic events involved in melanoma pathogenesis at somatic level, mutually-exclusive mutations of NRAS and BRAF genes were observed at quite same rate (about two thirds) in cultured and in vivo melanomas (either primary or metastatic lesions)." (PMID 19799798, 2009). "10-20% of melanoma have point mutations in codon 12, 13 or 61 of NRAS, which are almost always mutually exclusive with BRAF mutation." (PMID 19949544, 2009). "In a recent series of large-scale genetic studies, activating mutations were found in BRAF and NRAS oncogenes in a significant proportion of primary melanomas." (PMID 19642975, 2009). "Inhibition of mutant BRAF signalling in melanoma cell lines reduces proliferation, migration, increases susceptibility to apoptosis induction and ablates tumour formation in mice." (PMID 19724275, 2009). "Although MEK inhibition resulted in the downregulation of NFAT activity in BRAF mutant melanoma cells, this effect was also evident in BRAF wild-type CHL-1 cells, although the absolute levels of NFAT activation were substantially lower." (PMID 19724275, 2009). "Several proteins have been shown to be targeted by the BRAF/MEK/ERK signalling pathway in distinct tumours models (melanoma, colorectal and thyroid carcinomas); those proteins include cyclin D1 and p27Kip1, implicated in cell cycle regulation." (PMID 19878585, 2009). "BRAF a serine/threonine kinase, known to activate the MAPK pathway has been found mutated in several tumours, namely melanoma, colorectal carcinoma and thyroid carcinoma." (PMID 19878585, 2009). "The mutual exclusivity of BRAF and KRAS mutations in our ovarian carcinoma is consistent with previous findings in ovarian carcinoma, melanoma, and colorectal carcinoma." (PMID 19638206, 2009). "Some of the first reports have now appeared indicating that melanoma cells can also become resistant to BRAF inhibitors after continuous drug exposure." (PMID 19156138, 2009). "This study investigated the potential clinical utility of circulating free DNA (cfDNA) as a source of BRAF mutation detection in patients enrolled into a phase II study of AZD6244, a specific MEK1/2 inhibitor, in patients with advanced melanoma." (PMID 19861964, 2009).
melanoma (continued). "Knockdown of the BH3-family protein Mcl-1 using shRNA sensitised the melanoma cells to U0126-induced apoptosis, showing that overexpression of these key anti-apoptotic proteins in melanoma is a critical barrier to an effective BRAF/MEK inhibitor therapy." (PMID 19156138, 2009). "As the preclinical data support the selective activity of RAF and MEK inhibitors in BRAF mutant melanoma, it is logical to accrue patients to phase II trials with these agents." (PMID 19156138, 2009). "Given the pivotal role of BRAF in melanoma progression, it is somewhat surprising that these pharmacological inhibitors do not generally induce much apoptosis." (PMID 19156138, 2009). "Using a recently described inducible shRNA system, we have previously shown that signaling via oncogenic BRAF is essential for tumor initiation and maintenance in melanoma models." (PMID 19492075, 2009). "Treatment of melanoma cells with the BRAF inhibitor AZ628 led to the development of clones that maintained high phospho-ERK levels and continued to proliferate in the presence of drug." (PMID 19156138, 2009). "It is currently unclear how well the preclinical findings on the role of BRAF in melanoma cell lines match with the clinical observations on the role of BRAF in melanoma pathogenesis." (PMID 19156138, 2009). "In melanoma cells, activated BRAF suppresses MITF protein levels through ERK-mediated phosphorylation and degradation." (PMID 19828018, 2009). "Altogether these data show evidences that indicate that melanoma cells harboring oncogenic BRAF have a diminished response to metabolic stress." (PMID 19274086, 2009). "Although MAPK activation is a key step in the oncogenic transformation of melanocytes into melanoma, it appears that only a small minority of patients will benefit from the single-agent BRAF/MEK inhibitor treatment." (PMID 19156138, 2009). "Paired primary melanomas and lymph node metastases from same patients (N = 35) as well as melanoma cell lines (N = 18) were analyzed for somatic mutations in NRAS, BRAF, and p16CDKN2A genes." (PMID 19799798, 2009). "Inhibition of BRAF/MEK/ERK signalling using the highly specific MEK inhibitor PD98059 resulted in a reduction in NFAT transcriptional activity among all three melanoma cell lines." (PMID 19724275, 2009). "Conversely, a quite similar rate of BRAF-NRAS mutations (11/18; 61%) was detected in melanoma cell lines when compared to the uncultured melanomas." (PMID 19799798, 2009). "We here examined the relationship between alterations in NRAS, BRAF, and p16CDKN2A genes in both in vivo melanoma tissues (N = 35) from southern Italian patients and in vitro melanoma cell lines (N = 18)." (PMID 19799798, 2009). "For example, prolonged treatment of BRAFV600E-expressing melanoma cells with the BRAF inhibitor AZ628, leads to the development of clones that maintain high levels of phosphorylated ERK, which continue to proliferate in the presence of drug." (PMID 19724275, 2009). "BRAF, a serine-threonine kinase in the RAS/RAF/MAPK signalling cascade, is mutated in 60–70% of melanomas and, to date, represents the most common mutation in this disease." (PMID 18813315, 2008). "Real time PCR analyses with RNA from melanoma cell lines (n = 30) confirmed the BRAF-activation dependent up-regulation of BAALC." (PMID 18631381, 2008). "We tested this using the MEK inhibitor U0126, which efficiently blocked ERK activity in BRAF mutant melanoma cells." (PMID 18628967, 2008). "In summary, we show that oncogenic BRAF plays a critical role in regulating MITF expression in melanoma cells, using apparently opposing mechanisms to exquisitely regulate the levels of this critical transcription factor." (PMID 18628967, 2008). "We posit that because constitutively active ERK is so efficient at down-regulating MITF in BRAF mutant melanoma cells, it is necessary for the cells to rescue MITF expression to ensure that they can continue to proliferate and survive." (PMID 18628967, 2008).